OR51F1 (olfactory receptor family 51 subfamily F member 1)
Description:
Odorant receptor.
Synonyms: OR51F1P; OR11-21
Tractability: Antibody: UniProt places it where antibodies can reach, with medium confidence; UniProt predicts a signal peptide or a membrane-spanning region; its Gene Ontology location is reachable by antibodies, with medium confidence.
Gene: Protein-coding gene on chromosome 11 (4,768,979 to 4,769,938, reverse strand). Ensembl gene ENSG00000280021.
Subcellular location: Cell membrane
Pathways (Reactome):
Sensory Perception: Expression and translocation of olfactory receptors
Gene Ontology:
Molecular function: olfactory receptor activity; G protein-coupled receptor activity; signaling receptor activity
Biological process: cellular response to lipid; detection of chemical stimulus involved in sensory perception of smell; G protein-coupled receptor signaling pathway; system process
Cellular component: plasma membrane; membrane
Genetic constraint (gnomAD): Loss-of-function variants: 0 observed, 1.64 expected, observed/expected ratio (o/e) 0, 90% interval 0 to 1.5. That is too few expected variants to judge how well the gene tolerates losing a copy. Missense variants: 408 observed, 372.94 expected, observed/expected ratio (o/e) 1.09, 90% interval 1.01 to 1.19. Synonymous variants: 132 observed, 138.2 expected, observed/expected ratio (o/e) 0.96, 90% interval 0.83 to 1.1.
Homologues: Orthologues: chimpanzee OR51F1 (98% identical), macaque OR51F1 (89% identical), mouse Or51f1 (81% identical), rabbit OR51F1 (81% identical), dog OR51F1 (80% identical), rat Or51f1 (79% identical), mouse Or51f1e (79% identical), mouse Or51f1d (78% identical), rat Or51f1g (77% identical), pig OR51F1 (75% identical). Paralogues in human: OR9G1 (28% identical), OR10X1 (28% identical), OR11A1 (27% identical), OR11G2 (27% identical), OR11H12 (27% identical), OR9A4 (27% identical), OR11H2 (26% identical), OR11H1 (26% identical), OR11H6 (26% identical), OR9A1P (26% identical), OR9A2 (26% identical), OR11H4 (25% identical), and 21 more.